HOXB13 (homeobox B13)
Diseases named in the same sentence as HOXB13 in open-access papers (continued):
Sharing a sentence is not in itself a finding about the gene and the disease.
ovarian carcinoma (13 papers, 2010 to 2025). A malignant neoplasm originating from the surface ovarian epithelium. "In a search to find genes associated with EMT and aggressive phenotypes in ovarian cancer, siRNA inhibition of HOXB13 resulted in the restoration of cell–cell adhesion through the re-expression of E-cadherin." (PMID 39858044, 2025). "Cells transfected with HOXB13 siRNAs showed significant reduction in cell invasion, indicating that HOXB13 is associated with the invasive potential of ovarian cancer cells." (PMID 25944620, 2015). "Contrarily, a recent report described that knockdown of endogenous HOXB13 by RNA interference in human ovarian cancer cell lines was associated with reduced cell proliferation." (PMID 22808286, 2012). "HOXB7 and HOXB13 have been linked to increased instances of metastasis in breast and ovarian cancers and their overexpression in cell lines enhances many features of EMT." (PMID 21433221, 2011). "When we performed a screen to search for genes that are associated with EMT and aggressive characteristics of ovarian cancer cells using a limited siRNA library, we noticed that the transfection of siRNAs targeting HOXB13 induced morphological changes of SKOV3 cells." (PMID 25944620, 2015). "In addition to promoting proliferation, HOXB7 and HOXB13 are also thought to be associated with the invasive characteristics of ovarian cancer cells." (PMID 21906307, 2011). "ALX4, another tumor suppressor in the HOX family is involved in the promotion of ovarian cancer metastasis: ALX4, together with the other HOX protein HOXB13 promotes epithelial to mesenchymal transition factor SLUG in ovarian cancer cell lines." (PMID 40002854, 2025). "The induction of MET resulted in decreased cell invasion, implicating the key role HOXB13 plays in EMT in ovarian cancer and, therefore, is a promising biomarker for early detection." (PMID 39858044, 2025). "In this report, we show that two homeoproteins, HOXB13 and ALX4, can induce the expression of the EMT-associated transcriptional factor SLUG and promote invasion and EMT of ovarian cancer cells." (PMID 25944620, 2015). "A previous study reported that HOXB13 promoted ovarian cancer proliferation and conferred resistance to tamoxifen-mediated apoptosis, but the molecular mechanism of HOXB13-mediated tumor progression remains obscure." (PMID 25944620, 2015). "To gain further insight into the function of HOXB13 in ovarian cancer, we first examined the expression of HOXB13 mRNA in multiple ovarian cancer cell lines." (PMID 25944620, 2015). "In summary, we have shown that two homeoproteins, HOXB13 and ALX4, are associated with EMT and invasion of ovarian cancer cells." (PMID 25944620, 2015). "Promotion of EMT by either HOXB13 or ALX4 expression was also observed in another ovarian cancer cell line, NOS3." (PMID 25944620, 2015). "In this study, we show that two homeoproteins, HOXB13 and ALX4, are associated with epithelial to mesenchymal transition (EMT) and invasion of ovarian cancer cells." (PMID 25944620, 2015). "By contrast, HOXB13 is overexpressed in tumors, such as breast, cervical and ovarian cancers, as well as hepatocellular carcinoma." (PMID 25944620, 2015). "In ovarian cancer cells, a previous study showed that HOXB13 promoted cancer cell proliferation in vivo and conferred resistance to tamoxifen-mediated apoptosis." (PMID 25944620, 2015). "In addition, aberrant expression of HOXB13 has been reported in various types of cancers outside the CNS, including prostate, colorectal, breast and ovarian carcinomas." (PMID 40137996, 2025). "In ovarian cancer, HOXB13 promotes cancer cell proliferation and progression." (PMID 20504375, 2010). "Moreover, changes to MEIS/HOXB13 transcriptional regulation or interaction by HOXB13 mutations could enable MEIS proteins to pair with HOXA9 or HOXA10 to drive oncogenesis and progression, such as in leukemia or ovarian cancer." (PMID 32553107, 2020).
ovarian carcinoma (continued). "In this report, we showed that the depletion of HOXB13 induced reversion of EMT and suppressed invasion of ovarian cancer cells." (PMID 25944620, 2015). "Our results show that HOXB13/SLUG and ALX4/SLUG axes are novel pathways that promote EMT and invasion of ovarian cancer cells." (PMID 25944620, 2015). "HOXB13 has also been shown to enhance the proliferation of ovarian cancer cell lines SKOV-3 and OVCAR5 in vivo, and to promote the growth of a mouse ovarian cancer cell line in vivo and in vitro." (PMID 21906307, 2011).
colon carcinoma (10 papers, 2012 to 2024). "The top two genes identified to be differentially expressed between rectal and colon cancers were HOX family genes: HOXB13 was upregulated and HOXC6 downregulated in the rectal cancer samples." (PMID 38532103, 2024). "To verify the suppressive effect of HOXB13 on the progression of colon cancer in vivo, we constructed a xenograft tumor model using HOXB13 knockdown and HOXB13-overexpressing CRC cells." (PMID 31815008, 2019). "HOXB13 mRNA and protein expression was significantly decreased in colon cancer cell lines compared to normal control cells (P < 0.001)." (PMID 31815008, 2019). "IHC analysis was performed on 61 surgical specimens from patients with sporadic colon cancer to confirm the differential expression of HOXB13 at the protein level." (PMID 31815008, 2019). "First, the expression of HOXB13 was detected in human colon cancer cell lines (DLD1, RKO, HCT116, HT29, SW48, SW480, and LOVO cells) and a normal human colon mucosal epithelial cell line." (PMID 31815008, 2019). "Collectively, the results of the animal study further confirmed the antitumor properties of HOXB13 in colon cancer." (PMID 31815008, 2019). "To further verify HOXB13 expression in colon cancer patients and its prognostic significance, we examined the expression of HOXB13 in human tissues from our medical institution." (PMID 31815008, 2019). "In colon cancer cells, HOXB13, as a target of DNMT3b, was methylated at an upstream CpG island, and functioned as a tumor suppressor in primary colorectal tumors." (PMID 22808286, 2012). "HOXB13 inhibited colon cancer cell proliferation and induced apoptosis both in vitro and in vivo." (PMID 31815008, 2019). "Moreover, the wound-healing assay indicated that the downregulation of HOXB13 promoted cell migration, while the upregulation of HOXB13 had the opposite effect, suggesting that HOXB13 attenuates cell migration in colon cancer cells." (PMID 31815008, 2019). "However, it is interesting that the CGI we have targeted with our HOXB13 assay has previously been shown to undergo hypermethylation in colon cancer." (PMID 24490656, 2014). "It was reported that HOXB13 gene was a target of DNMT3b in colon cancer cells." (PMID 22808286, 2012). "In conclusion, our data highlighted an involvement of HOXB13, HOXC13 and HOTAIR in proximal colon cancers pathogenesis and in lymph nodes metastasis progression, highlighting the main role of these markers in prognosis of colon cancer patients." (PMID 30541551, 2018). "Specifically, the aberrant expression of the HOXB13, HOXC13 and HOTAIR in proximal colon cancers could add an important dowel in understanding molecular mechanisms related to tumor pathogenesis in this location." (PMID 30541551, 2018). "We have recently shown their de-regulation in colon cancer, describing the absence of expression of HOXA13, HOXB13, HOXC13 and HOXD13 in the normal colon mucosa, a slight increase in expression in the transitional mucosa, up to in many cases over-expressed in the tumor." (PMID 34208964, 2021).
gastric cancer (10 papers, 2015 to 2025). A primary or metastatic malignant neoplasm involving the stomach. "This dynamic relationship further solidifies the intricate interplay between FTO, HOXB13, and the underlying mechanisms that drive gastric cancer’s aggressive behavior." (PMID 38068717, 2023). "In gastric cancer, lower HOXB13 expression was associated with tumor differentiation, lymph node metastasis, and depth invasion." (PMID 38068717, 2023). "In our study, the three patients harboring HOXB13 missense variants presented either with intermediate- or high-risk disease and one of the three probands presented three different primary tumors, namely bladder and stomach cancer in addition to PrCa." (PMID 26176944, 2015). "Furthermore, it has been hypothesized that FTO might decrease HOXB13 promoter methylation levels, enhancing HOXB13 expression, which was linked to gastric cancer cell proliferation and invasion." (PMID 40481981, 2025). "HOXB13 expression was significantly lower in gastric cancer patients with lymph node metastasis, higher stage, and poorly differentiated (grade 3) tumors." (PMID 37627895, 2023). "Elevated levels of both FTO and HOXB13 expression have been observed in the context of gastric cancer." (PMID 38068717, 2023). "In another study analyzing the expression of FTO, HOXB13, and the m6A mechanism in gastric cancer, a positive correlation between FTO and HOXB13 was detected." (PMID 38068717, 2023). "The role of HOXB13 tumor suppressor has been also demonstrated in gastric cancer in which HOXB13 mRNA is significantly lower in primary tumors and its de-regulation is associated with a poorer differentiation, lymph node metastases, invasion and TNM stage." (PMID 31137568, 2019). "However, other scholars believed that HOXB13 may exert a tumor suppression effect given its relation to poor prognosis of right colon cancer and gastric cancer." (PMID 33315534, 2021). "Co-expression network analysis of datasets from the GEO database has identified four key genes involved in gastric cancer progression including ITGAX, chemokine (C-C motif) ligand 14 (CCL14), alcohol dehydrogenase iron-containing protein 1 (ADHFE1), and Homeobox B13 (HOXB13)." (PMID 39845786, 2024). "Interestingly, in gastric cancer, FTO was proposed to decrease HOXB13 methylation." (PMID 40481981, 2025).
prostate adenocarcinoma (10 papers, 2017 to 2025). "Cell lines originating from prostate adenocarcinoma samplesare most sensitive to deletion of the HOXB13 and TBX3genes." (PMID 41164275, 2025). "Four out of five prostate adenocarcinoma cell lines werehighly sensitive to the deletion of both the HOXB13 and TBX3genes: VCaP, LNCaP (clone FGC), PC-3 and 22Rv1." (PMID 41164275, 2025). "In summary, HOXB13 expression was detected in both benign prostatic tissues and prostate adenocarcinomas but its expression was lost or reduced in NEPCa tumors." (PMID 33531604, 2021). "In this paper, we report that HOXB13 is expressed in benign prostatic tissues and prostate adenocarcinomas, but its expression is decreased or lost in both human and mouse NEPCa." (PMID 33531604, 2021). "HOXB13 expression was detected in both benign prostatic tissues and prostate adenocarcinomas (AdPCa)." (PMID 33531604, 2021). "When we compared these t-SCNC cases with the prostate adenocarcinoma cases, we observed different accessibilities for the TFs AR, HOXB13, NKX3-1, and GRHL2." (PMID 31604930, 2019). "Thus, HOXB13 and TBX3are preferentially required for the proliferation of cell linesoriginating from prostate adenocarcinoma samples." (PMID 41164275, 2025). "We also tested SMYD3 abundance in a genetically engineered mouse model that recapitulates the development of human lethal prostate adenocarcinoma and metastasis through MYC overexpression and loss of Pten in prostatic luminal epithelial cells (Hoxb13-MYC+/− Hoxb13-Cre+/−PtenFl/Fl, or BMPC mice)." (PMID 37976356, 2023). "The fact that by ChIP-seq, SWI/SNF colocalizes with HOXB13 at active chromatin sites in prostatic adenocarcinoma cells, further supports the hypothesis that interaction between SWI/SNF and lineage-specific factors in PCa may be meaningful at the functional level." (PMID 33144576, 2020). "This study aimed to investigate the relationship between renal function parameters and distinctive molecular subtypes of prostate adenocarcinomas, defined by the immunoexpression of the SPINK1, ERG, HOXB13, and TFF3 markers." (PMID 37894380, 2023).
melanoma (9 papers, 2005 to 2025). A malignant, usually aggressive tumor composed of atypical, neoplastic melanocytes. "Accordingly, HOXB13 expression was either downregulated or mislocalised in several skin tumours, including melanoma, basal cell carcinoma, and squamous cell carcinoma." (PMID 15928669, 2005). "The expression of HOXB13 is known to be downregulated by hypermethylation of the promoter region in not only breast, but also colorecta, renal, prostate cancer and melanoma." (PMID 23950971, 2013).
prostate (9 papers, 2013 to 2025). "A recent study did not detect an effect of the G84E mutation on interaction with MEIS1, suggesting alternative mechanisms for HOXB13 mutations in driving prostate carcinogenesis beyond disruption of MEIS interaction." (PMID 32553107, 2020). "Nevertheless, as we have only used one cell line model and no androgen stimuli was performed, the mechanism by which the HOXB13 G84E mutation promotes prostate carcinogenesis remains unclear." (PMID 28050579, 2016). "Investigation of the transcription factors (TFs), such as the androgen receptor and its co-regulators FOXA1 and HOXB13, known to be important in prostate tumorigenesis, revealed their involvement in the differential expression of these genes." (PMID 40525903, 2025). "Our data show that specific HOXB13 mutations are involved in the acquisition of different cancer-associated capabilities and further support an oncogenic role for HOXB13 in prostate carcinogenesis." (PMID 28050579, 2016). "Our study supports the oncogenic role of HOXA13 in bladder cancer, as this gene is involved in the early and later stages of bladder tumorigenesis, while HOXB13 may play a tumor suppressive role in bladder cancer." (PMID 37627895, 2023). "Additionally, abnormal expression of HOXB13 has been detected in the development of leukemia, non-Hodkin’s Lymphoma, oral squamous cell carcinoma, glioma, colon, stomach and genitourinary cancers." (PMID 34983599, 2022).
bladder cancer (8 papers, 2019 to 2025). "The identification of nuclear HOXB13 expression in NMIBC contributed to better stratification of bladder cancer patients in relation to the risk of tumor recurrence." (PMID 37627900, 2023). "The association between HOXA13/HOXB13 protein expression and demographic/clinicopathological characteristics of the bladder cancer patients was determined by chi-square analysis." (PMID 37627895, 2023). "Of the 1418 bladder cancer patients enrolled in the study, three (0.2%) carried a HOXB13 mutation p.G84E (OR = 1.6; 95% CI 0.39–6.35; p = 0.8)." (PMID 34983599, 2022). "p.G84E mutation of HOXB13 gene was detected in three of 1418 (0.2%) bladder cancer cases and in six of 4497 controls (odds ratio [OR], 1.6; 95% CI 0.39–6.36; p = 0.8)." (PMID 34983599, 2022). "In the present study we noticed that mutation in HOXB13 gene were observed in three (0.2%) unselected bladder cancer patients and three (0.4%) unselected renal cancer patients." (PMID 34983599, 2022). "In addition, our study also aimed to determine the association of HOXA13/HOXB13 protein expression with various demographic and clinicopathological characteristics of bladder cancer patients." (PMID 37627895, 2023). "Although previous studies have shown the association of HOXA13 and HOXB13 with bladder cancer as well as the potential utility of HOXA13 as a biomarker for bladder cancer, findings from those studies are far from conclusive and require further robust validation." (PMID 37627895, 2023). "The aim of our study was to profile and characterize the protein expression of homeobox A13 (HOXA13) and homeobox B13 (HOXB13) genes in Malaysian bladder cancer patients." (PMID 37627895, 2023). "Future work will focus on validating the clinical significance of HOXA13 and HOXB13 as biomarkers for bladder cancer." (PMID 37627895, 2023). "Taken together, the dysregulation and delocalization of HOXB13 suggest that HOXB13 plays a crucial role in tumor evolution and is a potential prognostic biomarker for bladder cancer." (PMID 37627900, 2023). "In this study, both HOXA13 and HOXB13 were selected after conducting a comprehensive review of the existing literature on the dysregulation of homeobox genes in bladder cancer." (PMID 37627895, 2023). "Findings from our study showed that the HOXB13 protein was heterogeneously expressed in bladder cancer tissues and was mainly localized in the nucleus." (PMID 37627895, 2023). "When expressed, the HOXB13 protein was mainly localized in the nucleus of the bladder cancer cells, followed by nucleus and cytoplasm co-localization." (PMID 37627895, 2023). "This is crucial to thoroughly evaluating the potential of both HOXA13 and HOXB13 as biomarkers for bladder cancer." (PMID 37627895, 2023). "The protein expression of HOXA13 and HOXB13 in formalin-fixed paraffin-embedded (FFPE) bladder cancer tissues was determined by immunohistochemistry (IHC) analysis." (PMID 37627895, 2023). "IHC results show that the HOXB13 protein was heterogeneously expressed in bladder cancer tissues but was lowly expressed in normal bladder tissues." (PMID 37627900, 2023). "The putative oncogenic and tumor suppressive roles of HOXA13 and HOXB13, respectively, suggest their potential utility as biomarkers in bladder cancer." (PMID 37627895, 2023). "Positive HOXB13 expression was found in 57.8% (59/102) of the FFPE bladder cancer tissues." (PMID 37627895, 2023). "Thus, further investigation is needed to clarify the contradictory role of HOXB13 in bladder cancer." (PMID 37627895, 2023). "Therefore, our study aimed at profiling the protein expression of HOXA13 and HOXB13 in a cohort of formalin-fixed paraffin-embedded (FFPE) bladder cancer tissues from Malaysian bladder cancer patients." (PMID 37627895, 2023). "In the HOXB13 gene none of the tested mutation were found in 46 family cases of bladder cancer in first- and/or second-degree relatives." (PMID 34983599, 2022).
bladder cancer (continued). "The expression levels and nuclear localization of HOXB13 have also been suggested to be predictive markers for bladder cancer; however, the physiological function of HOXB13 in the brain remains completely unknown." (PMID 31878059, 2019). "Notably, the loss of HOXB13 protein expression was associated with progression to MIBC, suggesting HOXB13 may have a tumor suppressive role in bladder cancer." (PMID 37627895, 2023). "Their study found that cytoplasmic HOXB13 protein expression was significantly higher in MIBC compared to NMIBC, indicating HOXB13 promotes bladder cancer invasiveness." (PMID 37627895, 2023). "In contrast, low HOXB13 expression (including those with negative expression) was observed in 71.6% of the bladder cancer tissues analyzed." (PMID 37627895, 2023). "Hoxa13 and Hoxb13 are, for instance, known to have high expression in urinary bladder cancer Hox antisense intergenic RNA (HOTAIR) has been proposed as a marker in bladder cancer." (PMID 33402862, 2020). "As such, the role of HOXA13 and HOXB13 in bladder cancer is not well studied." (PMID 37627895, 2023).
breast tumors (7 papers, 2009 to 2018). "A higher HOXB13 expression in ER+ breast tumors always renders patients less likely to respond to TAM." (PMID 29471853, 2018). "The causes of a high HOXB13 expression in breast tumors are still not completely clear." (PMID 20649975, 2010). "To corroborate the DCIS-specific methylation profiles of TLX1, CGI 7:48, HOXB13, and HNF1B, we then extended the COBRA analysis to a series of primary breast tumors of different histological type and stage." (PMID 19250546, 2009). "Furthermore, HOXB13 and BRCA1 are all from “androgen-mediated pathway”, and are all found to be hypermethylated in breast tumors than normal tissues in our study." (PMID 23630576, 2013).